FCRL6 (Fc receptor like 6)
Description:
Acts as a MHC class II receptor. When stimulated on its own, does not play a role in cytokine production or the release of cytotoxic granules by NK cells and cytotoxic CD8(+) T cells. Does not act as an Fc receptor.
Synonyms: FcRH6; IFGP6; FLJ16056
Tractability: Antibody: UniProt places it where antibodies can reach, with high confidence; its Gene Ontology location is reachable by antibodies, with high confidence; UniProt predicts a signal peptide or a membrane-spanning region.
Gene: Protein-coding gene on chromosome 1 (159,800,511 to 159,816,262, forward strand). Ensembl gene ENSG00000181036.
Subcellular location: Cell membrane
Gene Ontology:
Molecular function: MHC class II protein binding; phosphatase binding; protein binding; protein phosphatase binding; transmembrane signaling receptor activity
Biological process: cell surface receptor signaling pathway; immune response
Cellular component: external side of plasma membrane; plasma membrane; cell surface
Genetic constraint (gnomAD): Loss-of-function variants: 50 observed, 52.7 expected, observed/expected ratio (o/e) 0.95, 90% interval 0.75 to 1.2. The upper end of that interval is the gene's LOEUF score, 1.2, which puts it in group 5 of 6, group 1 being the genes least tolerant of losing a copy. Missense variants: 571 observed, 538.04 expected, observed/expected ratio (o/e) 1.06, 90% interval 0.99 to 1.14. Synonymous variants: 213 observed, 207.18 expected, observed/expected ratio (o/e) 1.03, 90% interval 0.92 to 1.15.
Homologues: Orthologues: chimpanzee FCRL6 (98% identical), macaque FCRL6 (91% identical), pig FCRL6 (61% identical), dog FCRL6 (50% identical). Paralogues in human: FCRL3 (34% identical), FCRL5 (34% identical), FCRL2 (33% identical), FCRL1 (25% identical), FCRL4 (24% identical), FCRLA (23% identical), FCGR1A (21% identical), PECAM1 (19% identical), FCRLB (16% identical), FCGR2B (12% identical), FCER1A (11% identical), FCGR2C (10% identical), and 5 more.
Diseases named in the same sentence as FCRL6 in open-access papers:
FCRL6 is named in the same sentence as 23 diseases in open-access papers, as found by Europe PMC text mining. Sharing a sentence is not in itself a finding about the gene and the disease. The quoted sentences say what the papers report.
breast carcinoma (3 papers, 2014 to 2023). "Elevated FCRL6 expression also portended significantly higher PFS and OS in patients with intraductal breast carcinoma (n = 765) and estrogen positive (n = 782) tumor status (data not shown)." (PMID 33162991, 2020). "FCRL6 expression (log2) was heterogeneous among these cancer types but, in accord with our recent findings, lung adenocarcinomas (LUAD), cutaneous melanomas (SKCM), and breast carcinomas (BRCA) were among the tumors with higher median expression levels." (PMID 33162991, 2020).
melanoma (3 papers, 2020 to 2024). A malignant, usually aggressive tumor composed of atypical, neoplastic melanocytes. "The significance of FCRL6 in this arena has been recently demonstrated by its upregulation in HLA-DR+ tumor samples from melanoma, breast, and lung cancer patients who relapsed following PD-1 blockade." (PMID 33162991, 2020). "Like LAG3, FCRL6 was more highly expressed by MHCII+ melanomas and NSCLCs." (PMID 33162991, 2020). "Similarly, both FCRL6 transcript and protein expression was elevated in melanoma samples from patients who experienced relapse after progression on anti-PD-1 ICI therapy." (PMID 33162991, 2020). "By investigating its expression among The Cancer Genome Atlas (TCGA) tumor samples, we identify new evidence for the prognostic significance of FCRL6 in melanoma, breast, and lung cancer that collectively indicate its potential as a biomarker and therapeutic target." (PMID 33162991, 2020).
autoimmune disease (1 paper, 2021). A disorder resulting from loss of function or tissue destruction of an organ or multiple organs, arising from humoral or cellular immune responses of the individual to their own tissue constituents. "However, this CpG site is also an eQTM for five other genes in CD4+ T cells (TAGLN2, SLAMF8, DUSP23, PHYIN1 FCRL6), several of which have established autoimmune disease connections." (PMID 34946847, 2021).
Autoimmunity (1 paper, 2020). The occurrence of an immune reaction against the organism's own cells or tissues. "Thus, FCRL6 revealed unexpected heterogeneity in the developmental origins, regulation, and selection of natural Abs at the pre-BCR checkpoint with implications for autoimmunity and lymphoproliferative disorders." (PMID 32117244, 2020).
HIV-1 infection (1 paper, 2016). The type species of lentivirus and the etiologic agent of acquired immunodeficiency syndrome (AIDS). "FCRL6 has also been implicated in immune disorders as gene expression has been shown to be upregulated in the late stages of HIV-1 infection." (PMID 27446638, 2016). "Furthermore, FCRL6 expression was found to be upregulated in the late stages of HIV-1 infection, with FCRL4 similarly upregulated in HIV and hepatitis C infection." (PMID 27446638, 2016).
influenza (1 paper, 2019). An acute viral infection of the respiratory tract, occurring in isolated cases, in epidemics, or in pandemics; it is caused by serologically different strains of viruses (influenzaviruses) designated A, B, and C, has a 3-day incubation period, and usually lasts for 3 to 10 days. "The top five genes of each of the two clusters (NK cell activity; NK and T‐cell activity) that were most closely correlated with influenza antibody titers had seven genes (SPON2, AKR1C3, PRF1, FCRL6, GZMA, CSTK, NKG7) which belong to the aging signature genes of IL‐7Rαlow EM CD8+ T cells." (PMID 31044512, 2019).
leprosy (1 paper, 2023). Leprosy is a chronic infectious disease affecting primarily the skin and peripheral nervous system. "Because FCRL6 is chiefly expressed by cytotoxic T and NK cells, which are important in cellular defense responses against M. leprae, we speculate that FCRL6 subfunctionalization could be relevant for the adaptation of D. novemcinctus to leprosy." (PMID 36901962, 2023).
cancer (5 papers, 2020 to 2025). A tumor composed of atypical neoplastic, often pleomorphic cells that invade other tissues. "FCRL6 is an immunoregulator gene in cytotoxic T and NK cells, and the elevated level of this gene and its potential mechanistic role represented this gene as a favorable biomarker and therapeutic target in cancer." (PMID 39639867, 2024). "We next assessed survival in these cancer types according to FCRL6 expression." (PMID 33162991, 2020). "On the other hand, reduced engagement of the inhibitory co-receptors LAG3, a novel immunotherapeutic target in cancer and particularly B lymphomas, or FCRL6, due to decreased expression of its MHC-II ligand, could contribute to explaining the enhancement of anticancer immune responses by ICD." (PMID 36009442, 2022). "With respect to ‘immunocloaking’ the inhibitory receptors, Fc receptor-like protein 6 (FCRL6) and lymphocyte activation 3 (LAG3) are captured by MHC II on CD4+, CD8+ T cells and NK cells, thus achieving inhibition of immunity against cancer cells expressing MHC II." (PMID 36430404, 2022).
tumor (5 papers, 2020 to 2024). "Here we review recent developments related to members of the Fc receptor-like (FCRL1–6) immunoregulatory family with a specific focus on the FCRL6 molecule in cell-mediated immunity and its newly appreciated roles in tumor immunology." (PMID 33162991, 2020). "Evidence of a role for FCRL6 in tolerance and immune-evasion also comes from the tumor immunity." (PMID 36901962, 2023). "Given its discrete expression by cytotoxic T and NK lymphocytes and newfound role in tumor immunity, we explored the possibility that detection of FCRL6 in the tumor microenvironment could have prognostic clinical significance." (PMID 33162991, 2020). "A linear relationship was also evident for LAG3 and FCRL6 with the degree of HLA-DR+ tumor cells." (PMID 33162991, 2020). "Interestingly, high FCRL6 expression has been detected on NK cells within HLA-II+ solid tumors, and blocking of FCRL6 increased the functional response of NK cells as well as T cells toward HLA-DR+ tumor cells." (PMID 32133304, 2020). "Genes such as ADGRG1, TBX21, S1PR5, FCRL6, and FCGR3A showed relatively selective expression in tumor-reactive T cells (the average expression in bystander T cells < 0.5)." (PMID 39243082, 2024). "Staining of TNBC specimens showed that TIL co-expression of FCRL6 and LAG3 was strongly correlated with elevated tumor-specific HLA-DR expression." (PMID 33162991, 2020). "The highest FCRL6 transcripts were found in TNBC, followed by ER− > Basal > Her2− tumor samples." (PMID 33162991, 2020).
FCRL6 also shares sentences with these, for which no sentence is quoted: rheumatoid arthritis (2 papers); asthma (1); bacterial infections (1); blood disease (1); Graves disease (1); hematopoietic cancer (1); idiopathic thrombocytopenia purpura (1); infection (1); infectious disease (1); lung carcinoma (1); lymphoproliferative disorders (1); non-small cell lung carcinoma (1); psoriasis (1); systemic lupus erythematosus (1).